WSCD1 (WSC domain sialate O sulfotransferase 1)
Description:
Sialate:O-sulfotransferase which catalyzes 8-O-sulfation at the Sia-glycan level using 3'-phosphoadenosine 5'-phosphosulfate (PAPS) as a donor, forming 8-O-sulfated Sia (Sia8S)-glycans. Displays selectivity toward glycolipids such as GM1 gangliosides.
Synonyms: KIAA0523
Tractability: Antibody: UniProt predicts a signal peptide or a membrane-spanning region. PROTAC: its protein half-life has been measured.
Gene: Protein-coding gene on chromosome 17 (6,057,807 to 6,124,427, forward strand). Ensembl gene ENSG00000179314.
Subcellular location: Golgi apparatus membrane
Subcellular location (Human Protein Atlas): Nucleoplasm; Golgi apparatus
Gene Ontology:
Molecular function: sulfotransferase activity
Cellular component: Golgi membrane
Genetic constraint (gnomAD): Loss-of-function variants: 38 observed, 56.57 expected, observed/expected ratio (o/e) 0.67, 90% interval 0.52 to 0.88. The upper end of that interval is the gene's LOEUF score, 0.88, which puts it in group 3 of 6, group 1 being the genes least tolerant of losing a copy. Missense variants: 734 observed, 744.4 expected, observed/expected ratio (o/e) 0.99, 90% interval 0.93 to 1.05. Synonymous variants: 342 observed, 313.09 expected, observed/expected ratio (o/e) 1.09, 90% interval 1 to 1.2.
Homologues: Orthologues: chimpanzee WSCD1 (99% identical), macaque WSCD1 (98% identical), pig WSCD1 (93% identical), rabbit WSCD1 (88% identical), mouse Wscd1 (86% identical), rat Wscd1 (85% identical), guinea pig WSCD1 (84% identical), dog WSCD1 (75% identical), tropical clawed frog wscd1 (63% identical), zebrafish wscd1b (50% identical), zebrafish WSCD1 (42% identical), Caenorhabditis elegans T09E11.6 (6% identical), and 14 more. Paralogues in human: WSCD2 (48% identical), XYLT2 (17% identical), XYLT1 (16% identical), GCNT3 (9% identical), GCNT4 (8% identical), GCNT1 (8% identical), GCNT2 (7% identical), GCNT7 (7% identical).
Diseases named in the same sentence as WSCD1 in open-access papers:
WSCD1 is named in the same sentence as 9 diseases in open-access papers, as found by Europe PMC text mining. Sharing a sentence is not in itself a finding about the gene and the disease. The quoted sentences say what the papers report.
migraine (2 papers, 2018 to 2020). "Several of the genes exhibiting region-specific NTG effect have been associated with migraine in humans including Lrrc8 and Wscd1." (PMID 30618656, 2018). "Susceptibility for migraine loci on Wscd1 were identified on a large meta-analysis in humans." (PMID 30618656, 2018).
dyslipidemia (1 paper, 2025). "Moreover, several of the loci implicated in our analysis, such as those near SLC13A5, RABEP1, and WSCD1, overlap functionally with pathways previously associated with adiposity, dyslipidemia, and glucose regulation." (PMID 40429953, 2025).
glioblastoma (1 paper, 2022). The most malignant astrocytic tumor (WHO grade IV). "We also examined the effect of GZ17-6.02 on recently identified glioblastoma super-enhancer genes WSCD1, EVOL2, and KLHDC8A as well as the enzyme FADS2, which mediates ELOVL2 signaling." (PMID 35456993, 2022).
cancer (1 paper, 2025). A tumor composed of atypical neoplastic, often pleomorphic cells that invade other tissues. "Notably, seven UReg genes (GALNT14, KIAA0040, EPB41L1, ZNF469, BLNK, AK7, and WSCD1) are associated with the progression of various cancers in humans." (PMID 40241800, 2025).
tumor (1 paper, 2025). "Among them, the expression of TIPRAP, WSCD1, TCP11L2, DPP4, CAB39 and PDPK1 were down-regulated, while PARP1, DEPDC1B, CKAP2, ORMDL2, MRPL44, POLD4 and TMEM187 were increased in tumor group." (PMID 39949782, 2025).
WSCD1 also shares sentences with these, for which no sentence is quoted: depression (1 paper); glioma (1); neurological disorder (1); X-linked Nascimento-type intellectual disability syndrome (1).